CD40 (CD40 molecule)
Diseases named in the same sentence as CD40 in open-access papers (continued):
Sharing a sentence is not in itself a finding about the gene and the disease.
tumor (continued). "Despite the more restricted engagement of myeloid cell types in the tumor, the CD40/DC bsAb retains antitumor potency, further supporting the importance of activating the DC-T cell axis for the antitumor activity of CD40 agonists." (PMID 35911742, 2022). "It is interesting to consider this effect of CD40 stimulation on tumor fibrosis in the context of increasing the tumor’s accessibility to other therapeutics, including chemotherapies and cellular products." (PMID 34282297, 2022). "As a result of CNV analysis in pan-cancer targeting of these necroptosis risk model genes, FLT3, CD40, and FASLG genes have high CNVs in various tumor types." (PMID 36675706, 2022). "This robust anti-tumor effect correlated with the increase in intratumoral CD40+ DCs and the frequency of granzyme B+/IFN-γ+/TNF-α+ polyfunctional OVA peptide-specific CD8+ T cells." (PMID 36311701, 2022). "Agonist stimulation of macrophage activating receptors, including TLRs and the TNF receptor family member CD40, can trigger anti-tumor immune responses." (PMID 35158779, 2022). "Apigenin not only reduced the expression of different tumor-causing genes such as TNF-α, IL-6 and CD40, but also increased the activity of the tumor-suppressing STAT1 gene via IFN-γ gene inhibition." (PMID 35807549, 2022). "In this study, we aimed to investigate the roles of tumor cell-derived CCL2 on trastuzumab resistance and overcome the resistance by treatment with the anti-CD40-scFv-linked anti-HER2 (CD40 ×HER2) bispecific antibody (bsAb)." (PMID 35851310, 2022). "Using the KPC model of intraepithelial pancreatic tumorigenesis, cDC1 dysfunction and apoptosis was shown to be neutralized in vivo by IL-6 blockade, and CD40-agonist restored cDC1 maturation and abundance, resulting in enhanced control of tumor outgrowth." (PMID 35937775, 2022). "Upon activation, CD40 promotes antitumor T cell activation and reeducates macrophages to destroy tumor stroma." (PMID 36588677, 2022). "The clinical use of anti-CD40 agonist monoclonal antibodies (mAbs) is aimed at recruiting the immune system to fight the tumor cells." (PMID 35911742, 2022). "In one report, infusion of agonistic CD40 as a monotherapy in tumor-bearing mice resulted in functional deletion of tumor-specific CD8 + T cells." (PMID 34282297, 2022). "Membrane PDL1-restricted engagement of CD40 and 41BB but also inhibition of PDL1-induced PD1 activation were evaluated in coculture assays with PDL1-expressing tumor cell lines and 41BB, CD40 and PD1 responsible cell lines or T-cells." (PMID 35198053, 2022). "Owing to the fact that CD40 agonists make interactions with CD40 molecules on APCs and thereby potentiate their activation to prime tumor-specific CD8 + T cell responses, other studies have focused on CD40L role in inducing antitumor immunity." (PMID 34980128, 2022). "In CLL, CD40 is frequently over-activated in response to immunomodulatory effects, demonstrating that the tumor microenvironment can play a significant role in VEN response and resistance and offers possibilities for therapeutic intervention." (PMID 35778418, 2022). "CD40 engagement on HRS cells increased both tumor growth and survival, upregulated CD54, CD80, and IRF4 expression, augmented the secretion of IL-8, TNF-α, IL-6, LT-α and CCL5, decreased Fas-mediated apoptosis and increased NF-kB activation." (PMID 35626032, 2022). "The direct antitumor effect is established through the CD40/CD40L interaction between CD40L+ CAR-Ts and CD40+ tumor cells." (PMID 35634281, 2022). "The combination of K3-SPG-ISV/anti-CD40-ISV resulted in enhanced tumor suppression and prolonged survival longer than each monotherapy." (PMID 35136110, 2022). "CD40 agonists are reported to induce cytotoxic activity by TAMs in different tumor models, including pancreatic cancer." (PMID 35158779, 2022).
tumor (continued). "Whilst combining DMXAA with IL-2 or anti-CD40 antibody reduced tumor size, long-term survival was compromised as mice that were apparently cured of their tumors died." (PMID 36466911, 2022). "The results of this study revealed that GM-CSF + CD40L + CCL21 vaccination induced abundant tumor-infiltrating lymphocytes in tumors, which suggested the benefit of CD40 blockade in cancer treatment." (PMID 35453676, 2022). "One of the feasible approaches is to utilize the CD40 agonists, which can activate the DCs and promote the secretion of IL-12, furthermore turn the “cold” tumor to “hot” one." (PMID 35715855, 2022). "(A) Tumor size (in mm2) following treatments with anti-CD40, TNFα(i.e. (DC) adjuvant) and tumor-binding antibodies (n=5)." (PMID 36124553, 2022). "CD40L (also known as gp39, CD154, and TNFSF5), identified as the natural ligand of CD40, is a 50-kDa type II membrane glycoprotein that is also broadly expressed in various cells, including tumor cells." (PMID 36497444, 2022). "CD40 expression is positively correlated with type I anti-tumor T-cell responses and better survival." (PMID 36248969, 2022). "Specifically, maneuvers that release tumor antigens (such as administration of chemotherapy) must occur prior to CD40 agonist delivery." (PMID 36077755, 2022). "Agonistic CD40 targeting typically aims at the exploitation of the strong immunostimulatory activities of CD40 for tumor immunotherapy and vaccination against various infectious pathogens." (PMID 36361658, 2022). "Till date, distinct studies have suggested that the activation of CD40 is a significant mechanism in transforming so-called cold tumors into hot tumors (with prominent tumor infiltration of T cells), thereby sensitizing them to immune checkpoint Inhibitors." (PMID 36505472, 2022). "Previous studies have shown how the release of IL-10 from the tumor downregulates the expression of CD40 on DCs and DC precursors, suppressing their maturation and function." (PMID 36230990, 2022). "The previous studies demonstrated that FCGR3 on myeloid cells promoted CD40 antibody-mediated maturation of dendritic cells and activation of CD8+ T cells, and thereby drove the anti-tumor activity of agonistic CD40 antibodies." (PMID 36428599, 2022). "This cytotoxicity is mediated by the CD40/CD40 ligand axis, as CD40 ligand on DCs can interact with CD40 on tumor cells." (PMID 35715855, 2022). "The treatment with CD40 agonist monoclonal antibodies activates tumour-induced myeloid cells and reduces the suppressive function of murine and human MDSCs." (PMID 35454819, 2022). "For example, the TNFRSF members CD137 (4-1BB) and CD40 showed their potential as immunotherapy targets by stimulating the proliferation and cytotoxic activities of tumor-reactive CD8 T cells directly and indirectly, respectively." (PMID 35865955, 2022). "We observed that the combinational group (CD40 mAb and OK-432) endowed DCs with a stronger potential to stimulate T cells and prominent cytotoxicity to tumor cells." (PMID 35715855, 2022). "Further, CD40 agonist promoted the priming of tumor-specific CD8+ T cells in Batf3–/– mice, which occurs via monocytes/macrophages." (PMID 35393950, 2022). "We propose that CD40 hypoacetylation and, therefore downregulation, would promote angiogenesis and hide tumor cells from the immune system." (PMID 35740301, 2022). "Preclinical investigations showed that CD40-activated DCs were poised to prime or activate tumor-specific T cells." (PMID 35715855, 2022). "In line with this, animal studies have shown in recent years that checkpoint inhibitors or chemotherapeutic agents that promote proinflammatory processes in the tumor microenvironment have a synergistic antitumor effect with CD40 agonists." (PMID 36361658, 2022). "We show that local TCR cross-linking combined with CD40 activation reactivates preexisting TILs for efficient tumor control." (PMID 36073543, 2022).
tumor (continued). "CD40/CD40L signaling strengthens Nitric oxide synthase 2 (NOS2) expression, and production of nitric oxide and TNF-α through CD40 contributes to tumor elimination by adoptive cell transfer." (PMID 35806328, 2022). "As monotherapies, anti-CD40 mAbs have demonstrated evidence of promoting a macrophage-driven shift in the immune landscape of tumours." (PMID 35020853, 2022). "For these reasons, CD40 can turn upside down the immune suppression and drive anti-tumor as its blockade induce the secretion of IFNγ and a tumoricidal phenotype as demonstrated in preclinical models of pancreatic cancer and patients with cancer." (PMID 35664746, 2022). "Lastly, the intratumoral insertion of a nanofluidic-based drug eluting seed (NDES) is a minimally invasive method to provide sustained local delivery of OX40 and CD40 monoclonal antibodies into breast tumors and to avoid repeated injections in the tumor area." (PMID 35335881, 2022). "In a pancreatic cancer mouse model, dendritic cell vaccination and CD40-agonist combined treatment enable T-cell-dependent anti-tumor immunotherapy." (PMID 36303138, 2022). "Work has been ongoing for over 20 years to develop CD40 agonists with the aim to use them as adjuvants to push vaccination against various pathogens and/or to treat tumor diseases." (PMID 36361658, 2022). "To further study the functional role of CD40-CD40L, we used a blocking antibody to CD40 to disrupt the CD40-CD40L interactions in JQ-1-treated tumor-bearing mice." (PMID 35292660, 2022). "Mice given unmodified Neo-LNP showed a significant increase in CD69+ tumor-infiltrating T cells and the expression levels of CD40 in cDC1 (CD11c+ XCR1+)." (PMID 36311701, 2022). "Together with T-cell–inducing vaccines, OX40 and CD40 synergize with anti-PD-1 antibody to delay tumor progression and improve animal survival." (PMID 33503832, 2021). "Given a dual role of IL-6 in immunosuppressive cytokine-mediated pro-tumor effects immunity and CD40-mediated anti-tumor immunity, we next sought to test experimental therapy that combines CD40 agonist to maximize tumor immunity in anti-IL-6 treatment." (PMID 34103524, 2021). "This feature of APX005M further enhances its therapeutic value by preventing the depletion of CD40-expressing APCs, which are key mediators of the anti-tumor response." (PMID 33392713, 2021). "Established tumor regression occurred with the further addition of innate immune cell activators anti-CD40 and TLR9 agonist." (PMID 33803078, 2021). "Lately, a novel synergistic immunotherapy strategy based on dual targeting of IL-6 and CD40 has been proposed to potentiate anti-tumor immunity in animal GBM models." (PMID 34439380, 2021). "In this regard, myeloid activating agents (e.g., CD40 agonists) have been shown to induce macrophages with anti-fibrotic properties capable of remodeling the tumor microenvironment." (PMID 34202272, 2021). "CD40 ligation on DCs induces positive signaling that leads to their maturation and the release of IL-12, resulting in anti-tumor activity through T cell proliferation and differentiation towards a Th1 dominant state." (PMID 34439292, 2021). "More specifically, blockade of CCL5 after tumor establishment limited the anti-tumor effect of CD40 agonism plus immune checkpoint blockade." (PMID 34030676, 2021). "Activation of tumor-specific T cell responses has been shown to be strongly affected by activation of the CD40 signaling pathways on the APCs." (PMID 34768776, 2021). "This initial immunity to tumor implantation is dependent on cross-presenting cDC1 and requires CD40 to generate both CD4 and CD8 T cell responses to tumor-associated antigens in the draining lymph node." (PMID 33968757, 2021). "One promising alternative to ICIs is the use of CD40 agonist antibodies to prime APCs and invigorate anti-tumor T cells that have been inhibited by the suppressive TME." (PMID 33392713, 2021).
tumor (continued). "Consistently, our in vivo data show that Poly6 vaccination also led to a strong enhancement of CD40 expression in tumor infiltrated DCs compared to other DC costimulatory molecules (CD80, CD86, and MHC class II)." (PMID 33499256, 2021). "HT treatment alone slightly inhibited the tumor growth rate 1-week post treatment, but its combination with anti-CD40 antibody reduced tumor growth by > 70% compared to the control." (PMID 33391491, 2021). "A possible mechanism for the induction of apoptosis in tumor cells is the interaction between sCD40L and CD40 expressed on tumor cells." (PMID 33180184, 2021). "In a poorly immunogenic B16-OVA melanoma tumor model, poly (I:C) was used an adjuvant that combined with anti-CD40 and efficiently induced tumor rejection." (PMID 33986756, 2021). "In pancreatic cancer animal models, treatment with anti-CD40 agonist led to the recruitment of macrophages into the tumor and their polarization toward ECM-degrading cells by inducing the release of IFNγ and CCL2." (PMID 34831416, 2021). "In a recent phase 1b study, the combination of a CD40 activating antibody and standard chemotherapy (gemcitabine and nab-paclitaxel) resulted in tumor shrinkage in 20 of 24 patients." (PMID 33503832, 2021). "In the immunohistochemical analysis, CD40 was observed not only in stromal immunocompetent cells, but also in tumor cells of PDAC tissues." (PMID 34167573, 2021). "CD40 agonism given before anti-PD-1 therapy increased the anti-tumor response by activating T cells in a breast cancer model that exhibited an anti-PD-1 resistant immune cell phenotype." (PMID 33804039, 2021). "Anti-tumor effects of CD40 have attributed to its ability in the induction of Th1 anti-tumor responses and the impeding the suppressive effect of T-regulatory cells." (PMID 32902664, 2021). "Then, agonist anti-CD40 mAb was shown to stimulate the tumor killing activity of macrophages and to induce T cell-independent antitumor effects that involve macrophages, in neuroblastoma." (PMID 34572013, 2021). "The ligation of CD40 on macrophages, dendritic cells, and B cells leads to activation of these cells, enhances antigen presentation, and induces an effective T cell anti-tumor response." (PMID 34439097, 2021). "In fact, under otherwise identical conditions, response to RGS was reversed by (i) suppression of CD40 expression in the tumor cells by shRNA, and (ii) depletion of CD8+ Tc cells." (PMID 34092233, 2021). "The combination of anti-PD-1, anti-CD40, and chemotherapy provided long-term complete remission and survival in tumor-bearing KPC mice, a process that was T cell-dependent." (PMID 33804039, 2021). "Compared to single monoclonal antibody (mAb) or chemotherapy groups, the combination of anti-CD40/PD-1 with chemotherapy significantly impaired tumor growth and prolonged survival in advanced iCCA murine model." (PMID 34372912, 2021). "Further investigation is required to address if the antigen-independent activation of the CD40L/CD40 pathway will allow antigen-independent killing of stroma cells eliminating the tumor-supporting environment with subsequently better tumor control." (PMID 34912334, 2021). "For instance, tumor peptide loading on CD40-activated B cells resulted in effective induction of antigen-specific T cell responses after antigen presentation." (PMID 34576154, 2021). "Based on these results, we develop dual-targeting anti-IL-6 and pro-CD40 strategy to activate tumor immunity, sensitizing tumor to T-cell-based immunotherapies including checkpoint blockade." (PMID 34103524, 2021). "CD40 agonists also condition tumors for enhanced sensitivity to chemotherapy by modulating the extracellular matrix that surrounds tumor cells." (PMID 34101617, 2021). "Currently, research data demonstrate that these isoforms are differentially activated by CD40 to modulate effector signals like inflammation playing crucial roles in infectious diseases and tumour regression between others." (PMID 33536086, 2021).
tumor (continued). "Eleven of the fifteen CD40 CpG probes demonstrate hypermethylation in the tumor samples compared to the normal samples, while one CpG probe, cg07222575, shows the opposite trend, with a higher degree of methylation in normal samples." (PMID 33963293, 2021). "With concurrent activation, such as Polyinosinic:polycytidylic acid (poly I:C) and anti-CD40, the administered tumor antigen-receptor complex was shown to elicit effective immune responses and inhibit tumor growth." (PMID 34262573, 2021). "Effective primary tumour treatment strategies, aCTLA4 and aPD-1/CD40, were selected for treatment in the adjuvant setting (schematic)." (PMID 33835222, 2021). "Once activated, CD40 allows dendritic cells to drive the activation of antitumor T cells and re-educate macrophages to destroy the tumor stroma." (PMID 35003069, 2021). "It plays an important role in anti-tumor immunity, and agonists of CD40 have been shown to eliminate tumors in both pre-clinical and clinical settings, alone and in combination with other treatment modalities." (PMID 33804039, 2021). "Crosslinking of Fc by FcγRIIb expressed on tumor infiltrating immune cells is considered essential for the antitumor activity of human CD40 agonist antibodies, whereas engagement of the activating FcγRIIa inhibits this activity." (PMID 33408788, 2021). "CCL17 and CCL22 induced by CD40 stimulation on B-cell leukemia cells have been shown to attract CCR4+ tumor-specific T cells." (PMID 33666760, 2021). "This construct enables CD40L expressed on the CAR T cells to engage with CD40-positive tumor cells (resulting in direct cytotoxicity) and with antigen-presenting cells (APC)." (PMID 34809678, 2021). "Tumor-infiltrating B cells highly expressed HLA class II and CD40, were also identified, suggesting these cells play as antigen-presenting cells." (PMID 33431933, 2021). "Numerous vaccine strategies for cancer therapy are currently being evaluated, and the addition of CD40 agonist antibodies enhances the activity of tumor vaccines in nearly every case studied providing strong rationale for combination." (PMID 33392713, 2021). "Recently, it has been reported that Tip-DCs in the tumor microenvironment, guaranteeing effective CD8 T cells, mediate tumor rejection via CD40 activation." (PMID 33499256, 2021). "Another murine study, using an anti-CD40 agonist, found that increased tumour density was vital to its efficacy, which was dependent on CD8+ T-cells and independent of CD4+ T-cell help." (PMID 34960140, 2021). "In sum, our work uncovers a complex role for IL-6 in regulation of tumor immunity: IL-6 induces alternative Mφ polarization and anti-inflammatory immune suppression, whereas it stimulates pro-inflammatory CD40 expression via Stat3/HIF-1α in GBM." (PMID 34103524, 2021). "Agonistic CD40 antibodies have been shown to effectively inhibit tumor growth and prolong survival in several tumor models." (PMID 33804039, 2021). "APX005M is a highly potent inducer of innate and adaptive immune effector responses and represents a promising CD40 agonist antibody for induction of an effective anti-tumor immune response with a favorable safety profile." (PMID 33392713, 2021). "Studies have shown that the use of radiotherapy (RT) to induce tumor cell death and anti-CD40 to activate dendritic cells can result in in situ vaccination in animal models." (PMID 34765538, 2021). "The mechanism of agonistic CD40 therapy has classically been considered “licensing” of DCs for T cell priming, leading to the activation of tumor-specific T cells." (PMID 33497362, 2021). "In mouse models, anti-CD40 promotes T cell–dependent tumor regressions, particularly when combined with chemotherapy or immune checkpoint blockade." (PMID 34101617, 2021). "Monoclonal antibodies targeting immunostimulatory receptors such, as 4-1BB, DR5 and CD40, can stimulate anti-tumor immunity and provide therapeutic outcomes in multiple cancer types." (PMID 34680322, 2021).